MIR181A1 (microRNA 181a-1)
Synonyms: hsa-mir-213; MIR213; MIRN181A1; MIRN213; hsa-mir-181a-1; mir-181a-1; mir-213
Gene: MicroRNA gene on chromosome 1 (198,859,044 to 198,859,153, reverse strand). Ensembl gene ENSG00000207759.
Gene Ontology:
Biological process: miRNA-mediated post-transcriptional gene silencing
Cellular component: RISC complex
Homologues: Orthologues: chimpanzee ptr-mir-181a-1 (100% identical), macaque mml-mir-181a-1 (100% identical), pig ssc-mir-181a-1 (90% identical), guinea pig MIR181A1 (75% identical), mouse Mir181a-1 (73% identical), tropical clawed frog xtr-mir-181a-1 (62% identical), dog MIR181A1 (56% identical), zebrafish mir181a-2 (55% identical). Paralogues in human: MIR181A2 (58% identical), MIR181C (58% identical), MIR181B2 (42% identical), MIR181B1 (41% identical).
Diseases named in the same sentence as MIR181A1 in open-access papers:
MIR181A1 is named in the same sentence as 3 diseases in open-access papers, as found by Europe PMC text mining. Sharing a sentence is not in itself a finding about the gene and the disease. The quoted sentences say what the papers report.
mammary tumor (1 paper, 2022). "Similarly, several exosome-derived miRNA orthologs previously reported for increased expression in both canine and human mammary tumor cell lines, including MIR21, MIR106B, MIR181A1, MIR183, MIR200B, and MIRLET7G, were presented." (PMID 35765483, 2022).
MIR181A1 also shares sentences with these, for which no sentence is quoted: acute lymphoblastic leukemia (1 paper); leukemia (1).